CD81 (CD81 molecule)
Diseases named in the same sentence as CD81 in open-access papers (continued):
Sharing a sentence is not in itself a finding about the gene and the disease.
tumor (continued). "Importantly, we demonstrate an association between CD81 expression in HCC that is dependent on the degree of tumor differentiation, where poorly differentiated HCC express significantly higher levels of CD81 compared to the adjacent non-tumor tissue." (PMID 24662676, 2014). "Surprisingly, several CD9/CD81 functions, including promoting α3β1's association with PKCα and promoting α3β1-dependent tumor cell migration on LM-332, may not require CD151-dependent complex formation with α3β1 in this system." (PMID 23613949, 2013). "Moreover, CD81 has been shown to regulate cell growth in hematopoietic linage cells, and play a critical role in the tumorigenesis as well as in the migration of tumor cells via regulating the mitogen activating signaling and cells motility." (PMID 23349980, 2013). "Since PaCa-EVs uptake rate was found to be higher than non-tumor EVs; hence, we evaluated CD9 and CD81 expression in our EVs preparations." (PMID 41545338, 2026). "The anti-CD81 mAb 5A6 reversed the functions of CLDN1 overexpression in CRC malignant phenotypes and tumor xenograft growth." (PMID 42232600, 2026). "Even knock‐down of CD81 expression in ID8 cells, the exacerbation of tumour progression mediated by PCS was showed by in vivo imaging, calculating the number of tumour nodules and HE staining of omentum." (PMID 40604335, 2025). "The average optical density (AOD) of CD81 signal indicated the expression of CD81, and the AOD value of tumour tissues was higher than that of tumour adjacent normal tissues." (PMID 40604335, 2025). "All samples with significant tumor infiltration had a typical phenotype: CD45−, CD56+, CD81+, GD2+, B7-H3+." (PMID 41007693, 2025). "Apart from their involvement in TCR signaling, tetraspanins, such as CD81 and CD82, which are expressed in cancer cells, also influence the promotion or inhibition of tumor metastasis." (PMID 38515751, 2024). "The violin diagram shows that in HNSCC tissue, macrophages highly expressed four classic marker genes (CD63, CD9, CD81, TSG101) of exosomes, suggesting that TAM-EVs are highly secreted in the tumor microenvironment." (PMID 38602536, 2024). "For both subsets of γδ TRM, ZNF683 (Hobit), CD81, CD82, and IFNG expression is higher in the tumor compared to normal tissue." (PMID 39454432, 2024). "Uptake of CD9-RFP bearing EVs resulted in a more intense signal with respect to that from CD81-RFP fusions, confirming an impaired sorting and partial degradation of the latter in recipient tumor cells." (PMID 36579638, 2023). "Upon staining vesicles for typical tumor biomarkers, the presence of surface receptors CD63, CD81, and TSG-101 was demonstrated." (PMID 37886937, 2023). "The RT-qPCR assay results illustrated that both CD81 and CDKN1A were significantly downregulated in the tumor tissue compared adjacent normal tissue (p < 0.0001 of CD81 and p = 0.0029 of CDKN1A)." (PMID 37051592, 2023). "Tumor-evoked CD19+CD81+CD27+pSTAT3+ regulatory B cells producing IL-10 and TGF-β suppressed T cell responses in the spleen and supported tumor growth in experimental fibrosarcoma." (PMID 38136307, 2023). "We found that CD81 expression was significantly decreased in LUAD tumor tissues, especially in tumor tissues with local or distant metastasis." (PMID 38136327, 2023). "In addition, CITE-seq analysis also showed an increase in CCL22 expression in CD81+migcDC1s upon Flt3L treatment and could together with the CCL22 expression observed in migDCs be the cause of the increased CCL22 observed in the E0771 tumor supernatants." (PMID 37622122, 2023). "The main marker proteins of tumor exosomes are CD63 and CD81, which are widely found in the peripheral blood and body fluid." (PMID 38045487, 2023). "Cathepsin B cleavage site introduced between CD9/CD81 and RFP was recognized by tumor specific proteases allowing the release of the reporter protein." (PMID 36579638, 2023).
tumor (continued). "A variety of protein partners can interact with CD81, either to regulate attachment and uptake of viruses (HCV E2, claudin-1, IFIM1) or to contribute to tumor growth and dissemination (CD19, CD44, EWI-2)." (PMID 37046846, 2023). "It is well known that low expression of CD81 has more metastatic potential in HCC cell lines and the CDKN1A suppression facilitates cell cycle progression from the G1 to the S phase to promote tumor cell proliferation." (PMID 37051592, 2023). "When CD81 was stably overexpressed in CD81KO MDA-MB-231 cells tumorigenesis and tumor growth was rescued." (PMID 36193887, 2022). "A B-cell subset expressing activation markers (CD25+CD69+B7-H1+CD81+CD86+) and termed tumour-evoked Bregs (tBreg) induced the generation of Foxp3+Tregs, which inhibited anti-tumour responses." (PMID 35350071, 2022). "The exosome samples were first detected by Western blotting for exosomal markers, and the results showed all 4 types of tumor cell-derived exosomes expressed CD63 and CD81." (PMID 35200349, 2022). "To further determine the role of CD81 in CTC clustering, we utilized TN1 and TN2 PDX tumor cells, MDA-MB-231 cells, and 4T1 cells to analyze the phenotypic changes caused by siCD81/siCd81-mediated downregulation or CRISPR-Cas9-mediated gene depletion." (PMID 36193887, 2022). "IncuCyte images and quantified tumor cell aggregation curves of TN1 patient-derived xenograft (PDX) (I), MDA-MB-231 (J) cells upon CD81 KD (repeated at least three times)." (PMID 36193887, 2022). "After dissociation, CD81+ and CD81− TN1 PDX tumor cells were sorted on a fluorescence-activated cell sorter and then injected at dilutions of 1000 and 100 cells per injection into the mammary fat pads of NSG mice (n = 4 injections/group)." (PMID 36193887, 2022). "For example, circulating MM tumor cells are characterized by lower expression of adhesion molecules (CD138, CD56, CD117, and others) and activation molecules (CD38, CD28, and CD81)." (PMID 35407416, 2022). "Tumor cell-derived EVs carry a multitude of tumor antigens, are readily uptaken by DCs via high expression of exosome ligand, LFA1, facilitated by CD81, and are preferentially loaded into the MHC-II complex." (PMID 34207163, 2021). "In vitro and in vivo experiments demonstrated that suppressing CD81 by siRNA/shRNA enhanced radiation-induced cell killing and DNA damage of γ-H2AX formation, and delayed tumor xenograft growth of GBM." (PMID 33919192, 2021). "CD81+ and CD63+ EVs derived from both tumor cells and fibroblasts were found within both models, suggesting EV release and potential EV internalization by both cell types." (PMID 33968758, 2021). "Recently, EpCAM on tumor-derived EV membrane was also employed as a promising tumor surface marker, while the tetraspanin family of proteins, such as CD63, CD9, and CD81, was mainly used as EV universal markers." (PMID 34900726, 2021). "At the tissue level, CD9 was found to be predominantly localized at the cell membrane, whereas CD63, CD81, and CD82 were primarily found in the cytoplasm of the tumor samples." (PMID 34065085, 2021). "To determine the in vivo relevance of the secretion of CD81+CD63+EVs, we injected two 67NR-S and one 67NR-NS cell line into the mammary fat pad of BALB/c mice and monitored the tumor growth for six weeks." (PMID 34503207, 2021). "Our work demonstrated that both CD9 and CD81 are directly transcriptional targets of KLF4, which has been recognized and addressed as a tumor suppressor in various cancers." (PMID 32350244, 2020). "The expression of exosome markers, including CD81, ALIX, and TSG10, was detectable in both types of tumor exosomes, and an increased exosome secretion was observed in CT26-SDCSCs using NTA." (PMID 30683126, 2019). "To date, many tumor metastasis- and invasion-related studies have focused on CD9, CD81, CD82/KAI1, CD151, and TM4SF1." (PMID 30876464, 2019).
tumor (continued). "The tumor cell lines NCCIT, NTERA-2, and TCam-2 were transfected with two specific siRNAs to achieve knockdown of CD81, CBX-3, PHF-6, and ENSA." (PMID 31565104, 2019). "For example, MES GBMs (red arrows) were enriched for CAV1, CD44, CD63, RAB27A, SDCBP and SMPDL3A, while PN (blue arrows) tumours contained higher levels of transcripts for ANXA6, CD81, hnRNPA2B1, YBX1 (RNA binding proteins) and RAB35." (PMID 30034643, 2018). "This method is highly specific, allowing the isolation of only small EVs by using general small EV surface markers (e.g., CD81, CD9, and CD63) and even only small EV subpopulations, for example, tumor small EVs by using a tumor-specific marker." (PMID 29951374, 2018). "Recently, CD81 has been demonstrated to control MDSC and Treg function in a murine tumor model, which is the first in vivo evidence of tetraspanin function in antitumor immunity." (PMID 29896201, 2018). "We excluded markers that are known to be ubiquitously expressed on all nucleated cells (e.g. HLA) or on tumour cells (e.g. CD47) and focused our attention on five markers (CD57, CD59, CD81, CD164 and CD98) for further interrogation." (PMID 27590276, 2016). "Human tumor cell (K562, A549, and HCT116)-released exosomes showed vigorous expression of tetraspanins (CD9, CD63, and CD81) with the exception of CD9 on K562 exosomes at approx. 150 nm diameter." (PMID 27101102, 2016). "Expressed genes found in both the tumor group and the NPC with antitumor effect were Camk2, CD81, Kai1, TPT1 and AXL." (PMID 19558675, 2009). "THBS2 showed a significant correlation (P < 0.05) with tumor size in CD81 capture for all three groups but not for the CD9 and CD63 capture or the average capture (except the average capture in the all subject group, which has a P value of 0.02)." (PMID 40897818, 2025). "Since EVs express tetraspanin family proteins such as CD63, CD81, and CD9, circulating EVs could be detected by these proteins as well as other tumor-specific markers." (PMID 40679665, 2025). "The region containing tumor cells was characterized by a CD45−, CD56+, and CD81+ phenotype." (PMID 41007693, 2025). "Genetic engineering involves the fusion of tumor-targeting or tumor-penetrating peptides with transmembrane proteins, including LAMP2B, PDGFR, PTGFRN, CD63, CD9, and CD81, on EVs and the expression of the fused protein in donor cells, which produce EVs with the functional peptides on the surface." (PMID 38796692, 2024). "Furthermore, when we used super-resolution nanoimaging, we were able to confirm that the EBC of human lung tumor-bearing mice contained human tumor-derived EVs (positive for CD9, CD63, and CD81)." (PMID 38863869, 2024). "CAFs-Exo was found to be involved in tumor immune regulation through hsa-miR-139-5p, ACTR2 and EIF6, while PIGR, CD81, UACA and PTTG1IP may be potentially effective targets for the treatment of OSCC in the future." (PMID 37365497, 2023). "Recent data support the high level of versatility of the technique, with the identification of a series of housekeeping proteins, such as Rab5b, CD81, and CD63, and tumor-specific markers, such as PSA, but also surrogate tumor markers, such as Cav-1 and carbonic anhydrase." (PMID 37296842, 2023). "Accordingly, suppressing CD81 by siRNA/shRNA could enhance radiation-induced cell killing and DNA damage of γ-H2AX formation, and delaye tumor xenograft growth of glioblastoma." (PMID 36941633, 2023). "Although GPR56-expression, driven by transcription factor Hobit, inhibits the natural cytotoxicity of human NK cells by cis-interaction with the tetraspanin CD81, it appears that GPR56-expression in CD8 TILs cells defines a cytotoxic and tumor-reactive population." (PMID 35804934, 2022). "CD9 (Tspan4) and CD81 (Tspan28), depending on tumor type, can promote or suppress disease progression, while some other Tspan proteins, such as CD82 (Tspan27) and CD63 (Tspan30), have solely been established as tumor suppressors." (PMID 36143328, 2022).
tumor (continued). "While our previous work demonstrated that CD44 homophilic binding mediates tumor cell aggregation, in this study we propose that CD81 interacts with CD44 to promote intracellular CD44-CD81 heterodimer formation and possibly intercellular tetramer formation between two neighboring cells." (PMID 36193887, 2022). "Moreover, we transfected U251R and T98G cells with CD81 shRNA (shCD81) to establish the stable CD81-knockdown GBM cells and further investigated the influence of CD81 on tumor radioresistance in vivo." (PMID 33919192, 2021). "In most instances, the protein content of CAF-EVs is comparable between different tumor types and includes proteins normally enriched in exosomes such as CD9, CD63 and CD81 and proteins involved in exosome biogenesis like ESCRT-associated proteins, Alix, TSG101, HSC70 and HSP90β." (PMID 33899109, 2021). "CD81 is one of the surface markers used to identify MSC-derived extracellular vehicles (EVs) but does not have any reported immunomodulatory role for MSCs; however, CD81 coding gene is known to affect T regulatory (Treg) and myeloid-derived suppressor cell (MDSC) function, enhancing tumor growth." (PMID 34736534, 2021). "In summary, our findings have identified CD9 and CD81 as potential tumor suppressor genes in HCC, which may mediate KLF4-induced suppression of tumor cell growth via JNK signaling for the first time." (PMID 32350244, 2020). "Treatment of human breast cancer with dexosomes resulted in incorporation into tumors and subsequent expression of dexosome immunostimulatory molecules (e.g., CD86, CD81, MHCI/II + tumor antigen) on tumor cell surfaces, thus boosting tumor immunogenicity and T-cell engagement." (PMID 30191140, 2018). "Exosomes had a characteristic size distribution (mean diameter 88 nm, n = 3) and expressed Tumor Susceptibility Gene (TSG) 101 and CD81, which were absent in the larger diameter (100–1000 nm) extracellular vesicle population." (PMID 30397255, 2018). "In leukemic blasts however, any alteration of this function may influence tumor dormancy and treatment outcome in patients with AML with different levels of CD81 expression." (PMID 27566555, 2016). "These in vitro observations are supported by ex vivo staining of liver tissue showing increased CD81 expression in poorly differentiated tumor tissue compared to adjacent non-tumor areas, implicating CD81 as a tumor promoter." (PMID 24662676, 2014). "Our co-immunoprecipitation analyses with [3H]-palmitate-labeled tumor cells indicate that a number of proteins, including CD9 and CD81, were no longer associated with α3β1 integrin in the absence of CD151." (PMID 25356755, 2014). "Moreover, RMS cases were also CD45−, CD56+lo, CD90+ and CD57−; two expressed CD81+, CD9+ and CD58+ and one was partially positive for CD99 (40% of tumor cells ), a phenotypic pattern which was specific for this tumor subtype." (PMID 23472067, 2013). "Future studies should aim to elucidate the mechanism by which PKCα regulates α3β1 function in tumor cells, and the interplay between CD9/CD81, CD151, and other TEM-resident proteins such as the major CD9/CD81 partners, IgSF proteins EWI-2 and EWI-F/CD9P-1, in regulating metastatic cell behaviors." (PMID 23613949, 2013). "Intraperitoneal injections of GS-168AT2 in NCI-H460-xenografted Nude mice led to drastic inhibition of tumour growth, as well as to the downregulation of CD9, but not of CD81, in the tumour core." (PMID 21206492, 2011). "Western blotting showed that the exosome markers Hsp90 and CD81 did not significantly differ among the control exosomes, Exo-siNC, and Exo-siTMEM45A, were scarcely present in primary tumor cells, while α-Tubulin was expressed in primary cells but at lower levels in exosomes." (PMID 39910045, 2025). "Moreover, TNC+/CD81+ EVscorrelated with FLAIR hyperintensity, which besides tumor cell infiltration,might also be indicative of peritumoral edema." (PMID 40056466, 2025).
tumor (continued). "In addition, Cd81+migcDC1 also expressed high levels of Ccl22, which has been shown to promote the interaction with Tregs and CCL22 was also increased at the protein level in the tumor upon 9 days of Flt3L treatment." (PMID 37622122, 2023). "Indeed, also in flow cytometric analysis CD81+migcDC1s could be identified by their distinct expression of CD81 and XCR1 and were significantly increased upon Flt3L treatment in the E0771, TS/A and LLC tumor models." (PMID 37622122, 2023). "We compared mass spectrometry proteomic profiling of clustering and non-clustering TNBC patient-derived xenografts (PDXs) tumor cells and identified CD81, a tetraspanin protein enriched in extracellular vesicles (EVs), as one of the altered proteins upon CD44 depletion." (PMID 36193887, 2022). "The recognized exosomal markers CD63, CD9, and CD81, are not tumor-specific." (PMID 34707986, 2021). "Interestingly, an exosome marker CD81 was only detected in EVs in 2D cultures but not in the tissue-engineered 3D culture and the tension forces among the tumor cells appear to be related to this change in EV biogenesis." (PMID 33946403, 2021). "CD81 has not yet been clearly identified as either tumor growth suppressor or enhancer." (PMID 19558675, 2009). "Interestingly, EV marker CD63 was absent, suggesting this may be a tumor-specific feature, while CD81 was in enriched in RR-derived sEVs." (PMID 40568172, 2025). "However, studies on the role of CD81 in tumor radioresistance are hitherto lacking." (PMID 33919192, 2021). "Our results demonstrated that laminin, not fibronectin, is the primary target of tumor-derived sEVs containing CD63, CD81, or CD9." (PMID 40304687, 2025). "Meanwhile, when the cells were treated with B02, a Rad51 inhibitor, silencing CD81 would not sensitize GBM cells to radiation, which further illustrates that Rad51 acts as an effector protein of CD81 in tumor radioresistance." (PMID 33919192, 2021). "Therefore, we assessed whether correlation with worse PS (and thus greater tumour load) could be found with different levels of those exosomal proteins resulted to stratify patients in different clusters after hierarchical cluster analysis: EpCAM, CXCR4, CD81 and CD9." (PMID 31048929, 2019). "Addition of antibodies against CXCL1, CD81, and TPT1 had various effects either inhibiting the tumor proliferation or showing no significant changes upon the tumors." (PMID 19558675, 2009). "The fact that addition of an antibody enhances the suppressive effect of HiB5 and ST14A on tumor growth gives hints that the suppressive effect of these NPC is not due to their secretion of TPT1, CD81 and CXCL1, Gas6/Axl but to other factors." (PMID 19558675, 2009). "To expand the CD81 analysis in EpCAM+/− putative CTCs, we established a flow cytometry approach to gate single cells and clusters based on size channels (forward scatter and side scatter) as validated on clustering WT and non-clustering CD44KO tumor cells." (PMID 36193887, 2022). "Interestingly, we previously showed that the NK cell line KHYG-1 predominantly released EVs containing CD81 and not CD63, and that these vesicles contained low amounts of cytolytic proteins and lacked in killing activity towards tumor targets." (PMID 36189227, 2022). "Moreover, SP-IRIS demonstrated the presence of EVs that were double-positive for CD9, CD63, and CD81 and negative for the platelet marker CD41, which indicated low contamination of blood-derived EVs in the tumor EV isolates." (PMID 36531960, 2022).